RPL23AP82 (ribosomal protein L23a pseudogene 82)
Synonyms: MGC70863
Gene: Transcribed unprocessed pseudogene on chromosome 22 (50,798,655 to 50,799,123, forward strand). Ensembl gene ENSG00000184319.
Diseases named in the same sentence as RPL23AP82 in open-access papers:
RPL23AP82 is named in the same sentence as 1 disease in open-access papers, as found by Europe PMC text mining. Sharing a sentence is not in itself a finding about the gene and the disease. The quoted sentences say what the papers report.
cancer (1 paper, 2017). A tumor composed of atypical neoplastic, often pleomorphic cells that invade other tissues. "The top non-coding RNA was found to be a pseudogene named as RPL23AP82, which was deleted in 23 cancer types." (PMID 29657279, 2017).